BECN1 (beclin 1)
Diseases named in the same sentence as BECN1 in open-access papers (continued):
Sharing a sentence is not in itself a finding about the gene and the disease.
Granuloma (1 paper, 2021). A compact, organized collection of mature mononuclear phagocytes, which may be but is not necessarily accompanied by accessory features such as necrosis. "After 30 days of infection, there was an inverse relationship between the severity of granulomas or ROS formation and Becn1 expression." (PMID 34093961, 2021).
HCMV infection (1 paper, 2019). "Since ATG5 and BECN1 are enriched with purified virions, we wanted to know whether they accumulated during HCMV infection." (PMID 30872707, 2019).
hearing loss (1 paper, 2022). "Among these genes, ATG5, ATG7 showed the highest node scores in the mild hearing loss group, whereas MTOR, BECN1 showed the highest node scores in the severe hearing loss group." (PMID 35463035, 2022).
hippocampal atrophy (1 paper, 2021). "In the previous study, we found that G‐CSF significantly enhanced the levels of beclin‐1 and LC3 II/I ratio in DB/DB mice and reversed increases in the levels of NF‐κB, spatial memory, cognition was improved and the hippocampal atrophy of DB/DB mice were significantly ameliorated." (PMID 33459523, 2021).
hydatidiform mole (1 paper, 2015). A gestational trophoblastic disorder characterized by marked enlargement of the chorionic villi, hyperplasia of the villous trophoblastic cells and hydropic changes. "The total score averages of Beclin-1 immunoexpression for partial hydatidiform mole, complete hydatidiform mole and invasive mole were 2.5, 2.27 and 2.36." (PMID 26494988, 2015). "It is known that there were no Beclin-1 immunoexpression significant differences between complete hydatidiform mole, partial hydatidiform mole and invasive mole." (PMID 26494988, 2015).
Hypercholesterolemia (1 paper, 2017). An increased concentration of cholesterol in the blood. "Isolated hypercholesterolemia was associated with a significant reduction in expression of cardiac autophagy markers such as LC3-II, Beclin-1, Rubicon and RAB7 as compared to controls." (PMID 28330474, 2017).
Hyperinsulinemia (1 paper, 2018). An increased concentration of insulin in the blood. "Next, we found that the expression of major components of the autophagy process, including Beclin-1, Atg7, Atg3, Atg12-Atg5, free Atg12, Atg16L1, and LC3II was not affected by hyperinsulinemia." (PMID 29719598, 2018).
hypopharyngeal tumor (1 paper, 2015). "Similar results were observed in the tumor-bearing mice with Beclin-1 suppression, suggesting that autophagy inhibition may enhance hypopharyngeal tumor sensitivity to DDP." (PMID 25923669, 2015).
hypovitaminosis (1 paper, 2025). "Densitometric analysis revealed a significantly higher expression of BECN1 in both treated and treatment-naïve patients with normal vitamin D3 levels compared to those with hypovitaminosis (p < 0.05)." (PMID 40514685, 2025). "In treated patients a higher level of BECN1 was observed in individuals with normal vitamin D3 than those with hypovitaminosis." (PMID 40514685, 2025).
idiopathic dilated cardiomyopathy (1 paper, 2014). Decreased function of the heart associated with cardiac enlargement and congestive heart failure, of unknown cause. "Supporting such notion, transcript and protein levels of autophagic proteins (LC3-II, beclin-1, and ATG5-12) were also decreased in failing LV myocardium of patients with idiopathic dilated cardiomyopathy after explantation of a LV assist device." (PMID 24797938, 2014).
intestinal cancer (1 paper, 2024). "We found that autophagy-related pathway proteins changed after stable transfection with MLCK1 overexpression, i.e., LC3B II//Beclin-1 expression decreased and P62 expression increased, indicating that the level of death autophagy in intestinal cancer cells decreased." (PMID 38735014, 2024).
intracerebral hemorrhage (1 paper, 2025). A cerebrovascular disorder characterized by bleeding into one or both cerebral hemispheres including the basal ganglia and the cerebral cortex. "USP11 promotion of apoptosis has been reported in rat microglia after intracerebral hemorrhage, involving the deubiquitination of substrate protein Beclin 1 by USP11, which is consistent with the role of USP11 in neurological diseases reported in this study USP11." (PMID 39780069, 2025).
invasive ductal carcinoma of the breast (1 paper, 2015). "We examined the pathobiological properties of beclin-1, which is a key regulator of autophagosome formation in invasive ductal carcinoma of the breast, with a particular focus on the cancer microenvironment." (PMID 25955408, 2015). "In this study, we examined beclin-1 expression in archived pathological tissue specimens from patients with invasive ductal carcinoma." (PMID 25955408, 2015).
ischemia reperfusion injury (1 paper, 2022). Adverse functional, metabolic, or structural changes in ischemic tissues resulting from the restoration of blood flow to the tissue (reperfusion), including swelling; hemorrhage; necrosis; and damage from free radicals. "Meanwhile, the rapamycin specificity inhibited the expression of mTOR and upregulated the beclin-1 level to improve neuroprotective effects in ischemia reperfusion injury, where beclin-1 will stimulate the macrophage autophagy in the brain." (PMID 36505409, 2022).
ischemic diseases of the (1 paper, 2013). "Studies have shown that an increase in Beclin 1 expression can co-localize with caspase-3 activation, whereas the inhibition of autophagy reduces caspase-3 activation in some ischemic diseases of the CNS." (PMID 24143204, 2013).
Kawasaki disease (1 paper, 2023). A rare inflammatory disease characterized by an acute febrile, systemic, self-limiting, medium-vessel vasculitis primarily affecting children. "And ESR, BECN1, and LC3II mRNA expression are independent risk factors for IVIG-resistant Kawasaki disease." (PMID 38114939, 2023). "In the present study, BECN1 expression was found to be reduced in Kawasaki disease, a result consistent with that reported by Huang." (PMID 38114939, 2023). "mRNA expression of ESR, BECN1, and LC3II were independent risk factors for IVIG-resistant Kawasaki disease." (PMID 38114939, 2023). "ESR, BECN1, and LC3II mRNAs are independent risk factors for IVIG-resistant Kawasaki disease and may be involved in the development of IVIG-resistant Kawasaki disease." (PMID 38114939, 2023). "BECN1 was positively correlated with ATG16L1, while the incidence of IVIG-resistant Kawasaki disease, CAL, AST, NK% were negatively correlated with it (p < 0.05)." (PMID 38114939, 2023). "LC3II was positively correlated with BECN1 and negatively correlated with the incidence of IVIG-resistant Kawasaki disease, days in hospital, lymph node enlargement, IgG, and CAL." (PMID 38114939, 2023). "The autophagy markers ATG16L1, BECN1, and LC3II are downregulated in the expression of IVIG-resistant Kawasaki disease." (PMID 38114939, 2023). "RBC, HB, CK, CK-MB, ALB, A/G, LC3II, ATG16L1 were positively correlated with BECN1; the incidence of IVIG-resistant Kawasaki disease, length of stay, lymph node enlargement, perianal desquamation, CAL, IL-4, IL-6, CRP, PCT, SF, CD3 + CD4 + T, and r-GT were negatively correlated with BECN1." (PMID 38114939, 2023). "ATG16L1 0.42 (0.34, 0.50) vs. 0.49 (0.41,0.61), BECN1 0.46 (0.41, 0.63) vs. 0.83 (0.66,1), LC3II 0.41 ± 0.21 vs. 0.71 ± 0.19 were significantly downregulated in the IVIG-resistant Kawasaki disease group(P < 0.05), and LAMP2, p62 were not significantly different." (PMID 38114939, 2023).
left ventricular hypertrophy (1 paper, 2016). Enlargement of the LEFT VENTRICLE of the heart. "Pan et.al had found that miR-30a induced alterations in beclin-1 gene expression and autophagy in cardiomyocytes, angiotensin II induces down-regulation of miR-30 in cardiomyocytes and circulating miR-30 may be an important marker for the diagnosis of left ventricular hypertrophy." (PMID 26872060, 2016).
leishmaniasis (1 paper, 2020). Infectious disease that is transmitted through the bite of hematophagous female phlebotomine sand flies. "miRNAs also help in regulating autophagy by targeting BECN1, and it may have a significant impact on the treatment of leishmaniasis." (PMID 32849363, 2020).
lentivirus infection (1 paper, 2021). Virus diseases caused by the Lentivirus genus. "In order to study how the K414R mutation affected BECN1 expression, we examined the mRNA levels of Becn1, which were unchanged after K414R lentivirus infection in 293T cells." (PMID 34085745, 2021).
liver disease (1 paper, 2012). "In this study we evaluated the expression of Beclin 1 (one of the main autophagocytic agents, which bridges autophagy, apoptosis and both differentiation), and both pro- (Bad, Bax) and anti-apoptotic (Bcl-2, Bcl-xL) factors in liver samples from patients with different stages of liver disease." (PMID 22928777, 2012).
lung disease (1 paper, 2020). "The increasing expression of Bcl-2 and Bcl-xL inhibits autophagy and bacterial killing in human macrophages, suggesting that targeting the Bcl-2/Bcl-xL-Beclin 1 interaction may improving resistance to infection in patients with advanced lung disease." (PMID 32983259, 2020).
lysosomal storage disease (1 paper, 2023). A metabolic disorder caused by mutations in proteins critical for lysosomal function, including lysosomal enzymes, lysosomal integral membrane proteins, and proteins involved in the post-translational modification and trafficking of lysosomal proteins. "This evidence is in line with a previous report demonstrating that beclin-1 expression is not altered in several lysosomal storage diseases with normal sphingolipid traffic." (PMID 36983059, 2023).
malaria (1 paper, 2019). Malaria is a serious and sometimes fatal disease caused by a parasite that commonly infects a certain type of mosquito which feeds on humans. "Interestingly, the malaria pigment, hemozoin (HZ),—showed a moderate negative correlation with the mRNA levels of the three genes: ULK1 (rs = -0.57, P < 0.0001), BECN1 (rs = -0.40, P = 0.0088), and MAP1LC3B (rs = -0.42, P = 0.0053)." (PMID 31805150, 2019).
malignant germ cell tumor (1 paper, 2021). A gonadal or extragonadal malignant neoplasm that arises from germ cells. "Additionally, expression of Beclin 1 (BECN1), which is a target of miR-199a-5p, was shown to be higher in malignant germ-cell tumors than benign germ-cell tumors, which corresponds with their lower expression of miR-199a-5p." (PMID 33917022, 2021).
melanocytic neoplasm (1 paper, 2014). "In melanocytic neoplasms, similar results have also been observed, whereby Beclin-1 cytoplasmic protein and mRNA, as well as LC3 mRNA and LC3B protein, significantly decreased with tumor progression." (PMID 25202355, 2014).
meningioma (1 paper, 2024). A generally slow growing tumor attached to the dura mater. "Regarding meningiomas, the relationship between two autophagy markers, such as Beclin 1 and LC3B, with clinicopathological parameters has been previously carried out." (PMID 39131899, 2024).
microcephaly (1 paper, 2020). A congenital or acquired developmental disorder in which the circumference of the head is smaller than normal for the person's age and sex. "Alternatively, the low expression of IGF-1 detected in the postmortem brains of pups heterozygous for the Becn1 gene born to ZIKV-infected dams may have triggered neuronal loss and subsequently downregulated the microcephaly genes." (PMID 32498399, 2020).
mole (1 paper, 2015). "In the three types of mole, the total score averages of Beclin-1 immunoexpression were low." (PMID 26494988, 2015).
myelofibrosis (1 paper, 2025). A partial or complete replacement of the bone marrow stroma by fibrous tissue. "Several more favorable clinical myelofibrosis features were significantly associated with the upregulation of Beclin-1 and LC3B-II in the current study." (PMID 40217782, 2025). "Our research did not establish a statistically significant difference in the expression of Beclin-1 and LC3B-II in bone marrow cells of patients with primary and secondary myelofibrosis compared to the control group." (PMID 40217782, 2025). "The aim of our research was to investigate autophagy by measuring the expression of the Beclin-1 and LC3B-II genes in the bone marrow cells of patients suffering from primary and secondary myelofibrosis and examine the correlation with clinical and hematological parameters." (PMID 40217782, 2025).
nephrolithiasis (1 paper, 2025). The presence of a calculus in the pelvis of the kidney; this is most often composed of mineral salts and proteins. "In the early stages of nephrolithiasis, Beclin-1/ATG6 (BECN1)-nuclear receptor coactivator 4 (NCOA4)-mediated ferritinophagy disrupts iron homeostasis, resulting in iron overload." (PMID 40909330, 2025).
neuropathic pain (1 paper, 2025). Chronic pain caused by damage to nerve fibers. "In conclusion, our study demonstrated the role of BECLIN-1 in neuropathic pain-associated mechanical and thermal nociceptive hypersensitivity." (PMID 39809538, 2025). "Notably, autophagy is a key activator of inflammatory responses, and a loss of function in BECLIN-1 has been found to dysregulate immune responses, including microglia release of IL1-β, a cytokine which has consistently been implicated in mouse neuropathic pain models." (PMID 39809538, 2025).
NKT-cell lymphoma (1 paper, 2011). "Interestingly, low BECN1 expression was found to be an independent indicator of poor prognostic outcome (PFS and OS) in a recent study of 65 extranodal NKT-cell lymphoma cases." (PMID 21887344, 2011).
Osteoblastoma (1 paper, 2013). A rare benign bone-forming neoplasm usually arising from the spine. "The autophagy induction was also seen in salinomycin-treated MG-63 osteoblastoma cells, as the number of LC3B puncta positive cells and expressions of beclin-1/LC3B-II /ATG-7 were increased after salinomycin stimulation." (PMID 24358342, 2013).
Osteopenia (1 paper, 2024). Osteopenia is a term to define bone density that is not normal but also not as low as osteoporosis. "The trabecular osteopenia caused by Beclin-1 deficiency is interesting in that both trabecular thickness and separation are decreased, and trabecular number density increases." (PMID 38600946, 2024).
otitis media (1 paper, 2024). Inflammation of the anatomical structures of the middle ear, which is most often caused by an infectious process. "This conclusion is reinforced by our literature review, which supports the involvement of mTOR, LC3II/I, PI3K, beclin-1, FLIP, Akt, and Rubicon in the pathogenesis of otitis media." (PMID 38391409, 2024).
Pain (1 paper, 2025). An unpleasant sensory and emotional experience associated with actual or potential tissue damage, or described in terms of such damage. "To investigate the role of the BECLIN-1 protein in relation to nociceptive behavioral responses in a model of chronic neuropathic pain, we assessed pain-related behavior expressed by female and male WT and Bcl2AAA mice." (PMID 39809538, 2025).
pancreatic adenocarcinoma (1 paper, 2017). "Our transcriptome analysis of differentially expressed genes in the pancreatic adenocarcinoma AR42J cells revealed that gastrin upregulates the mRNA level of autophagy related genes (e.g. Sqstm1 and beclin 1 (E-MTAB-1268 and GSE32869)), suggesting that gastrin may induce autophagy." (PMID 28109268, 2017).
pancreatic insulinoma (1 paper, 2023). An insulin-producing neuroendocrine tumor arising from the beta cells of the pancreas. "In particular, pancreatic insulinomas (n = 24) showed a higher expression of the autophagic genes BECN1 (p < 0.001), MAP1LC3B (p < 0.001), SQSTM1 (p = 0.008), TFEB (p < 0.001), PRKAA1 (p = 0.038), and PRKAA2 (p = 0.019) compared to NF-pNET (n = 7)." (PMID 36835048, 2023).
peripheral nerve injury (1 paper, 2014). Injury to a peripheral nerve. "In this study, CCI-induced peripheral nerve injury did lead to autophagy induction on the SCDH and GDNF prevented the elevated expression of Beclin-1 due to CCI-induced nerve injury." (PMID 24642655, 2014).
post-traumatic stress disorder (1 paper, 2024). An anxiety disorder precipitated by an experience of intense fear or horror while exposed to a traumatic (especially life-threatening) event. "Moreover, gastrodin may have inhibitory effects on cell death and apoptosis by upregulating Beclin-1 and LC3 in the neurons of rats with post-traumatic stress disorder (PTSD), thereby improving their learning and spatial memory impairments." (PMID 39273485, 2024).
Premature ovarian insufficiency (1 paper, 2022). Amenorrhea due to loss of ovarian function before the age of 40. "Kuntai capsule can improve the estrous cycle and ovarian coefficient of rats with premature ovarian insufficiency, maintain the number of resting and growing follicles, and up-regulate the protein expression of growth differentiation factor 9, light chain 3 A-II, and Beclin 1 of rats’ ovaries." (PMID 36743924, 2022).
presbycusis (1 paper, 2022). Bilateral hearing loss caused by progressive degeneration of cochlear structures and central auditory pathways, typically associated with the aging process. "In the PPI network, autophagy-related genes ATG5, ATG7 showed the highest node scores in mild presbycusis; whereas MTOR, BECN1 showed the highest scores in severe presbycusis." (PMID 35463035, 2022).
pseudoexfoliation syndrome (1 paper, 2025). "Our study may gain importance as it is the first study in which Beclin 1, ATG5, ATG6, ATG12, p62, and LC3A/B autophagy markers are examined prospectively in the etiopathogenesis of pseudoexfoliation syndrome, comprehensively and with a control group." (PMID 40925341, 2025).
pulpitis (1 paper, 2021). Inflammation of the dental pulp. "Autophagy related genes such as autophagy related 5 (ATG5), ATG7, microtubule associated protein 1 light chain 3 (LC3) and beclin 1 (BECN1) were increased in pulpitis tissue." (PMID 34434926, 2021).
rectal adenocarcinoma (1 paper, 2023). "Moreover, rectal adenocarcinoma patients with low expression levels of BECN1 respond better to treatment than patients with higher levels of BECN1 expression." (PMID 36760166, 2023).
Rectal prolapse (1 paper, 2020). Protrusion of the rectal mucous membrane through the anus. "We also observed that about 70% of Becn1 −/− mice (N > 50) showed rectal prolapse around 4 months after birth." (PMID 32984329, 2020).
renal failure (1 paper, 2023). "We further examined whether Beclin-1 expression affected inflammatory factors that were previously identified to associate with renal failure and acute renal injury (AKI)." (PMID 36875088, 2023).
rosacea (1 paper, 2023). A chronic erythematous skin disorder that affects the face. "In the present study, we found that the mRNA expression of autophagy-related genes Becn1, Atg5, Atg10, and Atg12 was significantly increased in LL37-induced rosacea lesions after topical rapamycin treatment." (PMID 36937834, 2023).
SARS-CoV infections (1 paper, 2022). "It was found that 45.87% of the associated genes (CASP3, CASP9, MAPK1, MAPK3, XIAP) contributed to cytochrome C-mediated apoptotic response and 3.67% of the associated genes (BECN1, FXYD2, GSK3B, HSP90AA1, ITGB1, MAP1LC3B) contributed to SARS-CoV infections." (PMID 36164436, 2022).
ST Elevation Myocardial Infarction (1 paper, 2022). A myocardial infarction that produces elevation in the ST segments of the ECG. "Maintaining appropriate activation of autophagic flux and mitochondrial biogenesis by Tat-Beclin 1 or other agents may be used in future myocardial protection clinical trials in ST-elevation myocardial infarction patients." (PMID 35805195, 2022).
Testicular torsion (1 paper, 2024). Testicular torsion is when the spermatic cord to a testicle twists, cutting off the blood supply. "Eprosartan hold promise for managing testicular dysfunction arising from testicular torsion exerting antioxidant, pro-autophagic and anti-apoptotic effect via the activation of SIRT1/Nrf2/HO-1 as well as Beclin-1/AMPK/mTOR pathways." (PMID 38822026, 2024).